CSMD1 (CUB and Sushi multiple domains 1)
Diseases named in the same sentence as CSMD1 in open-access papers (continued):
Sharing a sentence is not in itself a finding about the gene and the disease.
cancer (59 papers, 2011 to 2025). A tumor composed of atypical neoplastic, often pleomorphic cells that invade other tissues. "In a previous study, CSMD1‐mut in cancer was found to be associated with increased TMB and favorable survival." (PMID 38087815, 2023). "In particular, CUB And Sushi Multiple Domains 1 (CSMD1) has caught our attention since it has been reported to be mutated in a variety of cancers." (PMID 36591517, 2022). "CSMD1 has been implicated in a variety of processes including development, complement control, neurodevelopment disorders, and cancer progression, though specific mechanisms of action have yet to be identified." (PMID 36553598, 2022). "Low expression of CSMD1 is also associated with poor survival outcome in the METABRIC early cancer cohort and is especially associated with poor survival outcome in the LumB subtype." (PMID 36153537, 2022). "Using genome-wide association studies, CSMD1 has been associated with several pathological processes, from neurodegenerative and psychiatric disorders to infertility and cancer." (PMID 34404439, 2021). "According to the previous studies, CSMD1 gene has recently been linked to a variety of pathological processes ranging from cancer and psychiatric disorders to neurodegenerative diseases, and they are related to each other." (PMID 33628416, 2021). "Mounting evidence indicates that the deletion of 8p23.2 or reduced expression of CSMD1 is associated with the development of many cancers 5-9." (PMID 31592231, 2019). "CSMD1 is localized at chromosome 8p23.2 and allelic imbalance and chromosomal aberrations of chromosome 8 are associated with development of many cancers." (PMID 27756250, 2016). "Aberrant splicing in CSMD1 has been associated with cancer susceptibility, while some studies report association between CSMD1 mutations and phenotypic variance in neuropsychological disorders, but it has no documented effect on any ocular phenotype." (PMID 27439461, 2016). "Although the function of CSMD1 is unclear, previous studies have shown that this transmembrane protein is engaged in a signalling cascade that regulates a variety of cell processes implicated in cancer formation such as proliferation and cell migration." (PMID 36553598, 2022). "In addition, a decrease in CSMD1 expression has been linked to poor prognosis and shorter survival of cancer patients." (PMID 34404439, 2021). "CSMD1 has been characterised, using a range of in vivo and in vitro approaches, and is implicated in various processes, such as testicular development, complement regulation, schizophrenia and in cancer progression." (PMID 33530646, 2021). "In addition to ADAM17, mutations of ARID1B and CSMD1 were identified in the SS samples isolated from 3 out of 8 cancer patients in this study." (PMID 30627328, 2018). "Somatic mutations in tumors may provide historical evidence for CSMD1 silencing by methylation in cancer progenitor cells." (PMID 23505554, 2013). "CSMD1 is frequently shown to be deleted, mutated, or methylated in many cancers." (PMID 23505554, 2013). "ZNF300, CSMD1, and CADM2 have been implicated in cancer cell proliferation, migration, and invasion, features mirrored by the invasive, immunologic, and angiogenic properties of placental cells." (PMID 40312437, 2025). "The involvement of CUB and Sushi Multiple Domains 1(CSMD1)_rs58499534 in our model aligns with previous research showing the crucial roles of CSMD1 in cancer-related processes." (PMID 39408230, 2024). "A further HNSCC study interrogating three publicly available genome-wide expression datasets found CSMD1-inactived cancers demonstrated a reduced prognosis." (PMID 36553598, 2022). "In this review, the differential analysis of CSMD1 expression between normal and cancer tissues was determined based on RNA sequencing data using tnmplot." (PMID 36553598, 2022).
cancer (continued). "CSMD1 has also been studied in other cancers, and decreased expression was found in lung, head and neck, breast, skin, colorectal, gastric, and ovarian cancers." (PMID 36291785, 2022). "This review will focus on CSMD1 and its roles in the complement system, neurodevelopmental diseases, cancer and metastasis, and EMT." (PMID 36553598, 2022). "Accumulating evidence supports that reduced expression of CSMD1 has a bearing on unsatisfactory prognosis in a variety of cancers." (PMID 35412956, 2022). "The top 10 frequently affected cancer-associated genes are HIRA (OG), CSMD1 (TS), CDH13 (TS), PRRX1 (OG), FHIT (TS), MGAM (OG), TBL1XR1 (OG), RHOA (OG), FGF14 (TS), and CNTNAP2 (TS)." (PMID 35013466, 2022). "Previous studies have shown that the deletion of 8p23.2 or reduced expression of CSMD1 has something to do with poor prognosis in many cancers 5-9." (PMID 31592231, 2019). "Among the genes with the mutations identified, they include Cancer Gene Census genes and other cancer-associated genes with three of which carried multiple mutations (ARID1B, CSMD1 and ADAM17)." (PMID 30627328, 2018). "In a xenograft model, expression of CSMD1 blocked the ability of cancer cells to metastasize to secondary sites in vivo, likely via inhibiting local invasion but not the extravasation into distant tissues." (PMID 27764775, 2016). "Surprisingly, homologous structures, namely the CUB and SUSHI domains, are shared between CSMD1 and other proteins that play important roles in cancer progression, such as SEZ6L and DMBT1." (PMID 27756250, 2016). "Our data offers support for the involvement of CSMD1 in different signaling pathways with an overall decrease of the cell signaling potential, correlating with the observed functional properties of cancer cells expressing CSMD1." (PMID 27764775, 2016). "Even though there was a small trend towards diminished extravasation of cancer cells to the lung in the CSMD1 group, this cannot explain the drastic difference in the occurrence of metastatic foci observed in the previous experiment." (PMID 27764775, 2016). "Conversely, stable silencing of CSMD1 expression in T47D cells enhanced cancer cell migratory, adherent and clonogenic abilities." (PMID 27764775, 2016). "Based on this understanding, we postulate that somatic mutations in CSMD1 accumulate in the stem cell compartment and disrupt CSMD1 expression prior to cancer development." (PMID 23505554, 2013). "CUB And Sushi Multiple Domains 1 (CSMD1), another gene with a role in cancer progression, is lost in approximately 40% of HNCs; reduced or absent CSMD1 is associated with decreased T cell infiltration." (PMID 38254801, 2024). "Recent studies have revealed a possible role for CSMD1 in immunotherapy for some cancer types." (PMID 36553598, 2022). "However, few studies of CSMD1 RNA expression and its target miRNAs in human cancers have been reported." (PMID 36291785, 2022). "Although the specific mechanisms of action for CSMD1 have not yet been uncovered, it has been linked to a number of processes including development, complement control, neurodevelopment, and cancer progression." (PMID 36553598, 2022). "In addition, we have identified large genes residing in common fragile sites to be significantly affected by deletions and contributing to cancer development, including CSMD1, WWOX and FHIT." (PMID 36726722, 2022). "Recently, several studies have suggested that CSMD1-inactivated cancers may respond to immune checkpoint inhibitors." (PMID 36553598, 2022). "We hypothesized that this distinct morphological architecture of CSMD1-expressing cells is a result of altered cellular protein expression and remodeling, characteristic for oncogenic transformation and progression of cancer." (PMID 34404439, 2021). "Taken together, CSMD1 diminishes the clonogenic properties of cancer cells." (PMID 27764775, 2016).
cancer (continued). "Interestingly, the ability of cells to initiate spheroid-colony growth in soft agar was inhibited in CSMD1 expressing cells, suggesting altered stem-like characteristics of cancer cells." (PMID 27764775, 2016). "The decreased adhesion in the presence of CSMD1 could be beneficial in the later step of metastasis when cancer cells attach to the target tissue." (PMID 27764775, 2016). "Cancer-specific hypermethylation of CSMD1 or other methylation markers could result from a particular mutational mechanism." (PMID 23505554, 2013). "Moreover, our results provided ample evidences indicating that the overexpression of CSMD1 gene, which functioned as a GC suppressor, could abolish the cancer-promoting activity of miR-642b-3p." (PMID 35412956, 2022). "Based on host genome integration frequencies, we found previously reported integration sites in cancer for genes like FHIT, CSMD1, and LRP1B and putatively many new ones such as those exemplified in CSMD3, ROBO2, and SETD3." (PMID 33810183, 2021). "HPV integration is most frequently detected in genic regions, most often cancer-related genes, such as oncogenes (e.g., TP63, MYC, ERBB2) or tumor suppressor genes (e.g., BCL2, FANCC, HDAC2, RAD51B, CSMD1) and to a lesser extent in miRNA regions." (PMID 34439243, 2021). "We found altered expression of several cancer-related molecules, as well as diminished expression of signaling receptors including Epidermal Growth Factor Receptor (EGFR), in CSMD1-expressing cells compared to control cells." (PMID 34404439, 2021). "Common CNLs negatively influencing DFS and cancer-specific OS harboured the feline orthologous of multiple HBC-related genes reported as commonly deleted including FOXP1, FBXO25, CSMD1, AGPAT5, PCM1, PTPRG, and PDGFRL15,19,27,28,41–43." (PMID 31969654, 2020). "This chromosomic region harbours the CSMD1, AGPAT5, TUSC3, DLC1, CLDN23, and MFHAS1 cancer-related genes." (PMID 30185896, 2018). "Moreover, the top three unstable methylation genes, TBC1D3H, CSMD1, and ROBO2, were all related to cancer." (PMID 35321246, 2022). "For example, FHIT, CSMD1, and LRP1B have been reported in cancer and lesions." (PMID 33810183, 2021). "The data suggest that the expression of CSMD1 does not influence the extravasation process, as the number of fluorescent cancer cells that entered via circulation to the lungs was not significantly different between the two groups." (PMID 27764775, 2016). "Here, we found no measurable effect of CSMD1 expression on the growth of primary tumors but we detected a striking difference in the ability of the cancer cells to metastasize to secondary sites." (PMID 27764775, 2016). "First we found that changes in the expression of CSMD1 did not modify the growth of the cancer cells, which simplified interpretation of the following migration and invasion assays." (PMID 27764775, 2016).
psychiatric disorder (13 papers, 2013 to 2025). A disorder characterized by behavioral and/or psychological abnormalities, often accompanied by physical symptoms. "For the identified genes, in the CSMD gene family associated with AD, CSMD1 was expressed in developing nerve cells and the expression of CSMD1 (Corrected P: 4.28E-43) was associated with cognitive function and mental illness." (PMID 35463515, 2022). "The Csmd1 KO mouse captures several major clinical phenotypes that have been associated to the human CSMD1 locus, both psychiatric disorders and somatic conditions." (PMID 24244513, 2013). "As demonstrated, knockout of the CSMD1 gene led to increased complement activity in the brain, resulting in the accumulation of the complement protein C3, which, in turn, contributed to the development of psychiatric disorders." (PMID 40362533, 2025). "As the four genes (CSMD1, PTPRD, LSAMP, and NPAS3), which remained significant also in the sex-specific analyses, have previously been implicated in other psychiatric disorders, pleiotropic effects could also be suggested." (PMID 39457114, 2024). "Abnormal axonal pruning may induce both neurodegenerative and psychiatric disorders, and CSMD1 has been reported to be correlated with cognitive functions including working memory and episodic memory." (PMID 39546599, 2024). "Nevertheless, we detected four inherited rare variants of unknown significance in four respective genes implicated in psychiatric disorders in the patient, including p.Arg1627Trp of LAMA2, p.Arg691Gly of TLR4, p.Pro1338Ser of CSMD1, and Arg182X of AGTR2." (PMID 37511534, 2023). "One mouse study that knocked out the CSMD1 gene revealed that it may be associated with the internal phenotypes of mental illness, including partial negative symptoms and a dull emotional response in SCZ." (PMID 30987620, 2019).
neurodevelopmental disorder (4 papers, 2021 to 2025). A behavioral and cognitive disorder with onset during the developmental period that involves impaired or aberrant development of intellectual, motor, or social functions. "According to the HGMD database, 2/3 of the 160 genetic variants identified in the CSMD1 gene have been associated with neurodevelopmental disorders." (PMID 40362533, 2025). "In summary, we identified a critical role for CSMD1 in brain development and biallelic CSMD1 variants as the molecular basis of a previously undefined neurodevelopmental disorder." (PMID 38816421, 2024). "While a genetic risk factor for neuropsychiatric disorders, the role of CSMD1 in neurodevelopmental disorders is unclear." (PMID 38816421, 2024). "Additionally, we anticipate that an MIM phenotype number will eventually be assigned to CSMD1, associating it with neurodevelopmental disorders and an autosomal recessive inheritance pattern." (PMID 40362533, 2025). "The strongest SNP associations were near genes previously identified for neuronal development and neurodevelopmental disorders, including PAPPA2 (rs147036913), SEMA6D (rs35175834), PDE4B (rs10789205), and CSMD1 (rs7830752)." (PMID 40490728, 2025).
neurological disorders (4 papers, 2022 to 2025). "CSMD1 is identified as being related to brain and neurological diseases in previous GWAS." (PMID 41300831, 2025).
CSMD1 also shares sentences with these, for which no sentence is quoted: liver cancer (4 papers); multiple sclerosis (3); amyotrophic lateral sclerosis (2); anxiety disorder (2); attention deficit-hyperactivity disorder (2); colorectal adenocarcinoma (2); dementia (2); migraine (2); myoclonic seizures (2); neonatal lupus (2); post-traumatic stress disorder (2); adolescent idiopathic scoliosis (1); arrhythmogenic right ventricular cardiomyopathy (1); benign prostatic hyperplasia (1); chronic bronchitis (1); chronic myeloid leukemia (1); cocaine dependence (1); cognitive decline (1); Crohn disease (1); developmental and epileptic encephalopathy (1); Dystonia (1); eating disorder (1); Epileptic encephalopathy (1); female infertility (1); Holt-Oram syndrome (1); juvenile myoclonic epilepsy (1); Kawasaki disease (1); learning disorders (1); leukemia (1); leukoplakia (1).
A further 23 diseases each share a sentence with CSMD1 in 1 paper.